BCL2L14 (BCL2 like 14)
Description:
Plays a role in apoptosis.
Synonyms: BCLG; BCL-G
Tractability: No criterion of Open Targets' tractability assessment is met for any kind of drug.
Gene: Protein-coding gene on chromosome 12 (12,049,844 to 12,211,084, forward strand). Ensembl gene ENSG00000121380.
Subcellular location: Cytoplasm; Cytoplasm, cytosol (Isoform 1); Endomembrane system (Isoform 2)
Subcellular location (Human Protein Atlas): Cytosol; Vesicles
Gene Ontology:
Molecular function: protein binding; protein kinase binding
Biological process: apoptotic process; positive regulation of extrinsic apoptotic signaling pathway; regulation of apoptotic process
Cellular component: cytosol; intracellular organelle; cytoplasm; endomembrane system
Genetic constraint (gnomAD): Loss-of-function variants: 19 observed, 29.05 expected, observed/expected ratio (o/e) 0.65, 90% interval 0.46 to 0.96. The upper end of that interval is the gene's LOEUF score, 0.96, which puts it in group 4 of 6, group 1 being the genes least tolerant of losing a copy. Missense variants: 324 observed, 352.73 expected, observed/expected ratio (o/e) 0.92, 90% interval 0.84 to 1.01. Synonymous variants: 123 observed, 140.1 expected, observed/expected ratio (o/e) 0.88, 90% interval 0.76 to 1.02.
Homologues: Orthologues: chimpanzee BCL2L14 (98% identical), macaque BCL2L14 (88% identical), rabbit BCL2L14 (72% identical), pig BCL2L14 (71% identical), dog BCL2L14 (69% identical), rat Bcl2l14 (69% identical), mouse Bcl2l14 (68% identical), guinea pig BCL2L14 (67% identical), tropical clawed frog bcl2l14 (25% identical). Paralogues in human: BCL2L12 (16% identical).
Diseases named in the same sentence as BCL2L14 in open-access papers:
BCL2L14 is named in the same sentence as 32 diseases in open-access papers, as found by Europe PMC text mining. Sharing a sentence is not in itself a finding about the gene and the disease. The quoted sentences say what the papers report.
breast carcinoma (6 papers, 2007 to 2023). "It was shown that attenuation of BCL2L14 expression accompanied the development of resistance to neratinib in breast cancer cells." (PMID 37031274, 2023). "BCL2L14 was upregulated by nanoparticulate tetraiodothyroacetic acid (tetrac), which reduced viable cell numbers more efficiently than unmodified tetrac in estrogen receptor-negative human breast cancer cells." (PMID 37031274, 2023).
colorectal cancer (5 papers, 2016 to 2023). A primary or metastatic malignant neoplasm that affects the colon or rectum. "Therefore, the possibility that rs2238126 affects the BCL2L14 gene and is related to colorectal cancer risk cannot be completely excluded." (PMID 27145994, 2016).
colon cancer (2 papers, 2016 to 2020). "The eQTL analysis from TCGA data also revealed that rs2238126 was an eQTL for the ETV6 and BCL2L14 genes in colon tumour." (PMID 27145994, 2016). "We found that rs2238126 was an eQTL for the ETV6 (PANOVA=3.46 × 10−3) and BCL2L14 (PANOVA=0.017) genes in colon tumour tissues but not in normal colon tissues (ETV6, PANOVA=0.169; BCL2L14, PANOVA=0.578)." (PMID 27145994, 2016).
colorectal tumors (2 papers, 2020 to 2023). "In this respect, disruption of Bcl-G activity might be linked with colon tumorigenesis as confirmed by a significantly reduced expression of BCL2L14 in human late-stage colorectal tumors." (PMID 37031274, 2023).
endometrial cancer (2 papers, 2022 to 2023). Primary or metastatic malignant neoplasm involving the endometrium (mucous membrane that lines the endometrial cavity). "Further, pterostilbene downregulation of oncogenic miR-663, whose expression is correlated with poor prognosis in endometrial cancer patients, led to induction of pro-apoptotic BCL2L14 in endometrial cancer cells in vitro." (PMID 36091792, 2022).
anaplastic large cell lymphoma (1 paper, 2012). Anaplastic large cell lymphoma (ALCL) is a rare and aggressive peripheral T-cell non-Hodgkin lymphoma, belonging to the group of CD30-positive lymphoproliferative disorders, which affects lymph nodes and extranodal sites. "The Bcl3 gene is a proto-oncogene candidate, currently considered to be a molecular marker of anaplastic large cell lymphoma and over-expression of the Bcl2l14 gene has been shown to induce apoptosis in cells." (PMID 22558084, 2012).
autoimmune disease (1 paper, 2024). A disorder resulting from loss of function or tissue destruction of an organ or multiple organs, arising from humoral or cellular immune responses of the individual to their own tissue constituents. "Our results showed that BCL2L14 is related to the differentiation and function of Tfh cells, which might be related to the aberrant expansion of Tfh cells, which is closely related to the progression of autoimmune diseases." (PMID 39080788, 2024).
Cerebral ischemia (1 paper, 2021). Restriction of arterial blood supply to the brain associated with insufficient oxygenation to support the metabolic requirements of the tissue. "A previous study proved that upregulation of miR-496 could decrease cerebral ischemia/reperfusion injury via negatively regulating BCL2L14 signaling pathway." (PMID 33724167, 2021).
Lassa fever (1 paper, 2021). A viral hemorrhagic fever that is caused by the Lassa virus, which is transmitted by contact with infected rodents; it is characterized by fever, headache, malaise, myalgia, and hearing loss. "Genes involved in extracellular matrix and cell-adhesion were also modulated, particularly during fatal Lassa fever (NID1, TIMP3, ITGA11, TGM2, MMP8/9, OLFM4, PCDH20, and CADM3), as well as some others involved in coagulation (SERPIN, TFPI2) and apoptosis (CLU, BCL2L14)." (PMID 33398113, 2021).
renal fibrosis (1 paper, 2024). A final common manifestation of a wide variety of chronic kidney diseases characterized by glomerulosclerosis and tubulointerstitial fibrosis. "Overexpression of BCL2L14 is associated with abnormal Tfh cell function and renal fibrosis." (PMID 39080788, 2024). "The overexpression of BCL2L14 in CD4+ T cells might induce renal fibrosis and inflammation by regulating the differentiation and function of Tfh cells." (PMID 39080788, 2024).
cancer (8 papers, 2008 to 2023). A tumor composed of atypical neoplastic, often pleomorphic cells that invade other tissues. "While several genetic alterations of BCL2L14 have been reported, gene deletions and amplifications prevail, which is also confirmed by the analysis of sequencing data for different types of cancer." (PMID 37031274, 2023). "One prominent target for FUBI modification is Bcl-G (Bcl2L14), a member of the Bcl-2 family of apoptosis-controlling proteins that frequently plays an important role in cancer development and therapy." (PMID 19671159, 2009).
tumor (8 papers, 2015 to 2025). "Some authors observed a high constitutive expression of BCL2-L14 in mice and human normal gastrointestinal tract; by contrast, this gene was down-regulated in inflammatory and tumor conditions." (PMID 35878173, 2022). "Similarly, BCL2L14::ETV6 enhances tumor invasiveness and taxane resistance in TNBC14." (PMID 41213951, 2025).
infection (2 papers, 2019 to 2024). The state of being infected such as from the introduction of a foreign agent such as serum, vaccine, antigenic substance or organism. "Genes upregulated for the BCL-2 family of antiapoptotic proteins (MCL1 in LMH cells, and BCL2A and BCL2L14 in CEK cells infected with either strain of ILTV), were in agreement with the notion that ILTV infection prevents apoptosis of infected cells, in order to prolong viral replication." (PMID 39392810, 2024).
BCL2L14 also shares sentences with these, for which no sentence is quoted: colitis (3 papers); hepatocellular carcinoma (2); prostate carcinoma (2); acute lymphoblastic leukemia (1); acute myeloid leukemia (1); B-cell acute lymphoblastic leukemia (1); chondrosarcoma (1); Chronic colitis (1); gastrointestinal disease (1); gastrointestinal tumor (1); inflammatory bowel disease (1); liver diseases (1); lupus (1); Myelodysplasia (1); osteoporosis (1); osteosarcoma (1); small intestinal tumors (1); tongue squamous cell carcinoma (1); ulcerative colitis (1).